SMARCA4 (SWI/SNF related BAF chromatin remodeling complex subunit ATPase 4)
Diseases named in the same sentence as SMARCA4 in open-access papers (continued):
Sharing a sentence is not in itself a finding about the gene and the disease.
tumor (continued). "Increased SMARCA4/BRG1 expression, for instance, has been shown to be associated with tumour development and invasiveness, while PBMR1/BAF180 was identified as a driver of progression to the castration-resistant state." (PMID 36611918, 2022). "These tumor have a distinctive IHC profile (loss of SMARCA4/BRG1, loss of SMARCA2/BRM, and expression of stem-cell markers SALL4, CD34, SOX2), although SOX2 is also commonly positive in NECs." (PMID 34663914, 2022). "During the current study, we also found mutations of Smarca4, Runx3 and Cxcr4 in early disseminated tumor cells." (PMID 36424557, 2022). "Based on these results, the tumor was classified as a thoracic SMARCA4‐deficient undifferentiated tumor." (PMID 36523385, 2022). "The investigation of an INI1 (SMARCB1) deficient neoplasm is highly recommended in such cases when BRG1 (SMARCA4) is retained." (PMID 35864317, 2022). "During the evolution of tumor cells, driver mutation occurred in a large number of oncogenic genes, including Smarca4, Cxcr4, Ctnnd2 and Ank1." (PMID 36424557, 2022). "The present case highlights two clinical issues (3.1 and 3.2) related to combination ipilimumab–nivolumab therapy in a patient with a thoracic SMARCA4‐deficient undifferentiated tumor." (PMID 36523385, 2022). "On the other hand, although the SMARCA4 loss is not directly targetable, Januario and collaborators demonstrated that inhibiting histone methyltransferase EZH2 was effective in SMARCA4-mutated cancer cell lines derived from various tumor types." (PMID 35884575, 2022). "AT/RT has been linked to mutations of SMARCB1 or, rarely, SMARCA4 genes, which function as tumor suppressor genes." (PMID 36276064, 2022). "In the sinonasal tract, to date only SMARCB1 (INI1) and SMARCA4 have been recurrently associated with specific tumor types." (PMID 35307773, 2022). "Combination ipilimumab–nivolumab was successfully administered to a patient with thoracic SMARCA4‐deficient undifferentiated tumor." (PMID 36523385, 2022). "Thoracic SMARCA4‐deficient undifferentiated tumours are ordinarily found as a huge mass with systemic metastasis, and the prognosis is poor." (PMID 35822082, 2022). "Multivariable analysis revealed solid tumor morphology, tumor SUVmax, clinical stage, SMARCA4 and SMAD4 alterations were independently associated with pathologic LN metastasis." (PMID 34290393, 2021). "The SMARCA4 gene undergoes an inactivating type of mutation to the gene that leads to a transcription error, causing loss of function of the subunit in the BAF complex and loss of BRG1 protein expression in the nuclei of the tumor cells." (PMID 34440689, 2021). "In summary, the SMARCA4-deficient tumors with a KRAS oncogenic activation are associated with a better prognosis, as the tumor will be less progressive, low grade, and with lower tumor burden as compared to a SMARCA4 intact KRAS co-mutated NSCLC." (PMID 34440689, 2021). "Nevertheless, in the murine small intestine, SMARCA4 loss in an Apc-deficient context attenuated aberrant Wnt signaling and prevented Wnt-driven tumor initiations." (PMID 33853662, 2021). "Based on computed tomography scan data a complementary immunohistochemical investigations were performed and they revealed that tumor cells exhibited a loss of expression of both SMARCA4 and SMARCA2 while SMARCB1 was retained." (PMID 33866513, 2021). "Similar to SCCOHT, our analysis in multiple NSCLC datasets of diverse tumor staging including the most comprehensive Director’s Challenge data set suggests that reduced SMARCA4 expression is associated with chemoresistance in NSCLC." (PMID 34518526, 2021). "Improvement in tumor suppressor activity in SMARCA4/A2 loss cases with BETi inhibition therapy has gained some interest which still needs more scrutiny." (PMID 34440689, 2021).
tumor (continued). "SMARCA4 correlated with tumor immunity and associated with different immune cells and genes in different cancer types." (PMID 34675941, 2021). "Anti-tumor activity in pre-clinical models of SMARCA4-deficient tumors have recently been identified in CDK4/6, AURKA, ATR, and EZH2 inhibition; hence, promising results await through future trials on the use of these agents alone or in combination with ICIs." (PMID 34440689, 2021). "In order to determine the potential role of SMARCA4 in tumor progression, we evaluated the association of the expression level of SMARCA4 with mutation levels of five MMR genes." (PMID 34675941, 2021). "With particular reference to SMARCA4, some previous studies have sought the vulnerabilities of SMARCA4-deficient tumours with a view to exploiting them for cancer treatment." (PMID 34262032, 2021). "It is important to consider SMARCA4-deficient thoracic sarcoma in the differential diagnosis of tumours showing suggestive morphologic features in patients of all ages, especially in the case of metastasis associated with thoracic mass." (PMID 33866513, 2021). "Heterozygous loss of SMARCA4 in mice leads to increased risk of developing cancer including lung and mammary gland, indicating that it is a tumor-suppressor gene." (PMID 33853662, 2021). "On the other hand, quantitative IHC for BRG1 can capture SMARCA4‐deficient tumor which is associated with SMARCA4 mutations." (PMID 33107184, 2021). "Overexpression of SMARCA4 in breast and late-stage pancreatic drives tumor cell proliferation and is associated with progressive disease and poor prognosis." (PMID 33513764, 2021). "This also raises the possibility to avoid the loss of SMARCA2 in SCCOHT using inhibitors of ATPase/Bromodomain, since the cell line survival is dependent on the SMARCA2 loss in a SMARCA4-deficient tumor." (PMID 34440689, 2021). "Here the authors show that SMARCA4-deficient tumours have significantly reduced levels of the histone demethylases KDM6s and a strong dependency on these demethylases for tumour growth, so that they are vulnerable to KDM6s inhibition." (PMID 34262032, 2021). "The somatic mutation of SMARCA4 leads to LoF, and its down-expression concurrently plays the same role in the tumor." (PMID 34771636, 2021). "The main tumor resulting from germline pathogenic variants in SMARCA4 is small cell carcinoma of the ovary, hypercalcemic type (SCCOHT)." (PMID 33692948, 2021). "On immunohistochemistry with SMARCA4 (BRG-1), the tumour cells showed significant loss of expression." (PMID 32884816, 2020). "We next queried if the SMARCA4 knock-down signature was associated with higher tumor grade, referred to as Gleason score risk groups in localized PCa36." (PMID 33144576, 2020). "This SMARCA4-WT tumour demonstrated somatic mutations in genes encoding two other subunits of the SWI/SNF remodelling complex: AT rich interactive domain 1 A (ARID1A) and AT rich interactive domain 1B (ARID1B)." (PMID 31844183, 2020). "Some studies have linked the proximity of the SMARCA4 locus to the STK11 locus (another well-known LUAD tumor suppressor gene) and the loss of heterozygosity that recurrently affects the short arm of the chromosome 19 in LUAD." (PMID 33321963, 2020). "The molecular pathogenesis of this tumor remained elusive until our group recently identified recurrent SMARCA4 loss as driver genetic event in the majority of cases." (PMID 32507920, 2020).
tumor (continued). "Null mutations of SMARCA4 lead to death during embryogenesis in mouse models; however, mice with heterozygous mutations of SMARCA4 were instead predisposed to tumor development." (PMID 32629987, 2020). "The SMARCA4 gene is one of the tumor suppressor genes that encode the BRG1 protein, a subunit of the SWI/SNF complex." (PMID 32972432, 2020). "For example, SMARCB1 deficient cells require residual SWI/SNF function, because concomitant loss of SMARCB1 and SMARCA4 blocks tumor development." (PMID 31123059, 2019). "Together, these tumor gene expression data support that SMARCA4 loss results in reduced CCND1 expression in SCCOHT." (PMID 30718512, 2019). "Similar to ARID1A, many SMARCA4 mutations are predicted to inactivate, suggesting that it functions as a tumor suppressor." (PMID 31123059, 2019). "The gene encoding the ATPase of the chromatin remodeling SWI/SNF complexes SMARCA4 (BRG1) is often mutated or silenced in tumors, suggesting a role as tumor suppressor." (PMID 29391527, 2018). "Within iCluster 2, we identified a group of tumours with shared features including mutations in SMARCA4 (encoding the SWI/SNF factor BRG1), increased DNA methylation (rightmost samples) and relatively unaltered SCNA profiles." (PMID 28052061, 2017). "Previously, only four familial cases of SCCOHT were sequenced, and all affected patients were found to carry SMARCA4 mutations with second somatic mutations in their tumours." (PMID 27866340, 2017). "Affected members in both families and the associated tumours were found to carry SMARCA4 germline and somatic mutations, respectively, leading to loss of SMARCA4 protein expression in the tumours." (PMID 27866340, 2017). "The SMARCA4 gene was sequenced in germline and tumour DNA of both patients and a germline nonsense mutation was found: c.175C>T; p.Asn59*." (PMID 27866340, 2017). "Frequent germline and somatic mutations of SMARCA4 in small cell carcinoma of the ovary of hyper calcemic type (SCCOHT) suggested a tumor suppressor role." (PMID 27701467, 2016). "Genome sequencing of SCCOHT tumor biopsies revealed both, germline and somatic mutations of the SMARCA4 gene including a stop codon mutation p.Arg1077* and a frameshift p.Pro1180fs." (PMID 26436697, 2015). "Another SMARCA4 homozygous mutation – insertion of a single guanine nucleotide c.2352insG, was found in the other tumor investigated." (PMID 25886974, 2015). "Smarca4-/- (Brg1, Snf2b) mouse embryos die at the peri-implantation stage while Smarca4+/- mice are indeed predisposed to tumour development." (PMID 26571505, 2015). "In AC, mutations were found in tumor suppressors SMARCA4/BRG1 (SWI/SNF-related, matrix-associated, actin-dependent regulators of chromatin) and ARID1A (AT-rich interaction domain 1A) – both members of the SWI/SNF complex, in 8% and 10% of tumors, respectively." (PMID 24722523, 2014). "The first somatic mutation of SMARCA4 was described in an NSCLC tumor, and expression inactivation by mutation was also frequently found in NSCLC cell lines." (PMID 25391308, 2014). "The tumor showed loss of SMARCA4 (also known as BRG1), high Ki-67 (∼50%), and rapid growth." (PMID 41799407, 2026). "A biopsy of the tonsillar mass confirmed a SMARCA4-deficient undifferentiated tumor." (PMID 40978837, 2025). "The biopsy pathology was diagnosed as tumor with SMARCA4 deficiency." (PMID 41170461, 2025). "A further SCLC tumor exhibited a SMARCA4 loss-of-function mutation." (PMID 41373665, 2025). "Such metabolic mapping is critical, as SMARCA4-deficient undifferentiated tumors often present with heterogeneously enhancing masses where CT alone cannot reliably distinguish between necrotic and metabolically active tumor compartments." (PMID 40978036, 2025).
tumor (continued). "The pathogenic heterozygous SMARCA4 p.G256* truncating mutation, associated with loss of SMARCA4 protein function, is the central genetic alteration underlying the development of this SMARCA4-deficient tumor." (PMID 41395620, 2025). "This study emphasises the development of PROTACs that selectively and effectively target SMARCA2 in vivo through the conversion of non‐selective SMARCA2/4‐binding ligands, thereby potentially offering a new therapeutic opportunity for patients with tumours harbouring SMARCA4 mutations." (PMID 39779467, 2025). "Moreover, once-daily treatment with CP-C27 led to marked suppression of tumor growth in SMARCA4/SMARCA2-deficient DMS114 and SS18–SSX fusion Fuji xenograft models, again with no adverse effect on the body weight of mice." (PMID 39625239, 2025). "The mutation frequency of SMARCA4 varies significantly across different tumor types." (PMID 41170461, 2025). "SMARCA4-UT was diagnosed with the loss of SMARCA4 (BRG1) expression in the tumor cells." (PMID 40406754, 2025). "SMARCA4-deficient undifferentiated tumor is a rare and clinically aggressive malignancies characterized by the inactivation of the SMARCA4 gene (BRG1), a key regulator of chromatin remodeling within the mammalian switch/sucrose non-fermentable (SWI/SNF) complex." (PMID 40978036, 2025). "The sarcomatous component was identified as a tumor characterized by SMARCA4 deficiency." (PMID 41170461, 2025). "Interestingly, tumours with SMARCA4 loss, a hallmark of poorly differentiated NSCLC, showed high expression of NE markers, particularly SYP." (PMID 41025426, 2025). "The SMARCA4 has been identified as a tumor suppressor gene, located on chromosome 19p13, encoding the BRG1 protein, which is an important component of the SWI/SNF chromatin remodeling complex, which has transcriptional regulation and DNA damage repair functions." (PMID 40313929, 2025). "SMARCA4-deficient undifferentiated tumor demands prompt diagnosis and aggressive treatment." (PMID 40978036, 2025). "Similarly, another critical component of the SWI/SNF chromatin remodeling complex, loss of SMARCA4 function, has been linked to increased genomic instability, altered cell differentiation, and enhanced tumor invasiveness." (PMID 39941707, 2025). "Furthermore, the absence of Claudin-4 expression led to the diagnosis of a Mesenteric SMARCA2-deficient yet SMARCA4-preserved undifferentiated tumor." (PMID 40012963, 2025). "Furthermore, treatment with PD-1/PD-L1 ICIs in another two patients with SMARCA4-deficient NSCLC led to marked tumor regression and improved performance status." (PMID 39888726, 2025). "Gastric SMARCA4-deficient tumor may include gastric SMARCA4-deficient carcinoma and gastric SMARCA4-UT." (PMID 38877473, 2024). "Gene panel testing using the OncoGuideTM National Cancer Center (NCC) Oncopanel System (National Cancer Center, Tokyo, Japan, and Sysmex Corporation, Kobe, Japan) revealed two pathogenic somatic mutations of SMARCA4 in the tumor (c.2866_2867delC>T [p.L956fs*2] and c.3543delC [p.Q1182fs*34])." (PMID 38903333, 2024). "SMARCA4 immunohistochemistry showed loss of nuclear expression in the tumor cells." (PMID 38656564, 2024). "Collectively, we speculated that the loss of function via trans biallelic mutations in SMARCA4 led to tumor development in this case." (PMID 38903333, 2024).
tumor (continued). "In addition, SMARCA4-mutated NSCLCs are associated with a higher likelihood of negative or low programmed cell death ligand-1 (PD-L1) expression (p =0.03) and higher tumor mutational burden (TMB) as compared to wild-type (WT) cases (p < 0.001)." (PMID 39063938, 2024). "These CGP results further support the pathological diagnosis of a SMARCA4‐deficient tumor." (PMID 38923369, 2024). "Moreover, the ablation of SMARCA4 is implicated in mitigating the proliferation of osimertinib-resistant neoplasms, providing a plausible explanation for the observed therapeutic challenges in this patient." (PMID 39465834, 2024). "Specifically, some studies suggest that SMARCA4 functions as a tumor suppressor and that mutations and low expression in this gene are associated with a poor prognosis for patients with tumors, whereas the opposite conclusions have been reached in other studies." (PMID 39322625, 2024). "The lack of staining for SMARCA4 on the cell block obtained from the EBUS-TBNA of the lymph nodes and the lesion, combined with the results of the other immunohistochemical analyses, was sufficient to confirm a diagnosis of thoracic SMARCA4-deficient undifferentiated tumor." (PMID 39886719, 2024). "In this paper, we will focus on the role of the two most frequently mutated subunits of the SWI/SNF complex, ARID1A and SMARCA4, in tumors and their molecular mechanisms, as well as the anti-tumor therapeutic strategies that have been identified for the corresponding mutations." (PMID 39697230, 2024). "Thoracic SMARCA4‐deficient undifferentiated tumor was initially described in 2015." (PMID 39648153, 2024). "Potential mechanisms underlying ICI efficacy in SMARCA4-UT include (a) high tumor mutation burden, (b) enhanced T-cell cytotoxicity due to SWI/SNF complex deficiencies, (c) impaired regulatory T cell activation, and (d) complex interactions with PD-L1 expression." (PMID 39360100, 2024). "SMARCA4-UT has a high tumor mutation burden, which supports the potential efficacy of ICIs." (PMID 39497014, 2024). "Histopathological examination of the surgically resected specimen revealed undifferentiated tumor cells with eosinophilic cytoplasm, eccentrically located vesicular nuclei, prominent nucleoli, and frequent mitoses, similar to SMARCA4-deficient thoracic sarcoma." (PMID 38903719, 2024). "In addition to the SMARCA4 mutation and retained SMARCA4 expression, the primary tumor in this study also displayed partial loss of SMARCB1 and SMARCA2 expression." (PMID 38201285, 2023). "SMARCA4 mutations have varying effects that are largely dependent on tumour and mutation type." (PMID 37433987, 2023). "IHC stainings revealed a loss of SMARCA4 in all tumor cells." (PMID 37919824, 2023). "This suggests that although the mutant allele of SMARCA4 can be successfully translated into messenger RNA, nonsense-mediated decay of the truncated protein may cause complete loss of BRG1 expression in ATRT tumour cells that carry this mutation." (PMID 37433987, 2023). "In addition to pivotal driver and tumor-suppressor mutations, several mutations were detected in some cancer genes associated with chromatin remodeling and RNA splicing, including SMARCA4 and SMARCA2 (SWI/SNF chromatin-remodeling factor genes)." (PMID 38102134, 2023). "Recent studies have suggested the use of CDK4/6 inhibition in treating SMARCA4-deficient tumours." (PMID 36883553, 2023). "However, it is well documented that WNT and Group 3 MB tumours commonly experience loss-of-function missense SMARCA4 mutations that occur in the ATPase domain." (PMID 37433987, 2023). "However, combined MYC overexpression and SMARCA4 loss successfully induced tumor formation in vivo after orthotopic transplantation in recipient mice." (PMID 37919824, 2023). "However, in the current group of patients, two patients with SMARCA4‐dNSCLC had common genetic locus mutations, and the tumor‐type transformation in one of them was curious." (PMID 37184108, 2023).